PDCD4 (programmed cell death 4)
Diseases named in the same sentence as PDCD4 in open-access papers (continued):
Sharing a sentence is not in itself a finding about the gene and the disease.
tumor (continued). "The suppression of PDCD4 by miRNA-21 may be influenced by the secretome of adjacent cells in the tumour microenvironment (TME)." (PMID 35847932, 2022). "miR-21 upregulation in IBD encourages T cell activation in UC remission patients and may potentially reduce tumor suppressor PDCD4 expression in CD3+ T cells, promoting inflammatory progression and eventual cell proliferation towards cancer." (PMID 35955886, 2022). "As PDCD4 might be pro-inflammatory, questions therefore arise regarding the function of PDCD4 as a tumour suppressor during inflammation, a state that promotes neoplastic transformation, particularly in cancers of the GI tract." (PMID 35847932, 2022). "Another study in steroidogenic human ovarian granulose-like tumor cell line has shown that upregulation of miR-155 by targeting PDCD4 and regulating PI3K/AKT and JNK pathways could enhance proliferation, migration, and invasion of cells." (PMID 35402235, 2022). "However, the burgeoning number of publications examining changes in the expression of PDCD4 in transformed cells and tumours exemplifies the potential importance of this protein in cell regulation." (PMID 35847932, 2022). "It was concluded that Linc 00472 could act as a tumour suppressor by sponging miRNA-196a2 and thereby increasing PDCD4 expression." (PMID 35847932, 2022). "PDCD4 expression was also found to positively correlate with MEG3 expression in tumour cells." (PMID 35847932, 2022). "Evidence of PDCD4 as a tumour suppressor was first demonstrated in murine epidermal JB6 cells." (PMID 35847932, 2022). "PTEN and PDCD4 are known to have tumor-suppressing functions." (PMID 35682901, 2022). "PDCD4 is a tumor suppressor and can bind with EIF-4A to limit the available content to form EIF-4F." (PMID 36271348, 2022). "Upregulation of miR-23a/b by targeting PDCD4 could increase tumor growth and inhibit apoptosis in GC." (PMID 35402235, 2022). "Given that PDCD4 is a specific type of tumor suppressor, downregulation of PDCD4 by progestin may be one of the factors contributing to progestin’s poor therapeutic effectiveness and association with progestin resistance." (PMID 36551694, 2022). "Likewise, Pten and Pdcd4 protein expression was restored in the miR-21 antagomir-treated cohort of tumor-bearing Gp130F/F mice when compared to the scrambled antagomir-treated cohort." (PMID 35053428, 2022). "Corroborating a possible inverse association between PDCD4 and inflammation, inducible overexpression of the miRNA-21, a micro-RNA that suppresses translation of the tumour suppressor, results in diminished expression of PDCD4, intestinal inflammation and CRC in transgenic zebrafish." (PMID 35847932, 2022). "miR-21 is activated through gut dysbiosis and targets tumor suppressors PDCD4, BTG2, and TPM1, along with modulating the PI3K/AKT pathway by repressing PTEN to activate ERK and AKT, which induces the downstream NF-κB pathway to release inflammatory cytokines TNF-α, IL-6, and IL-1β." (PMID 35955886, 2022). "PDCD4 has been confirmed as a tumor suppressor gene involved in multiple cancer-related process." (PMID 36115854, 2022). "Indeed, the RBP, lupus antigen (La), together with HuR, binds to the 3′UTR of PDCD4 (Programmed Cell Death Protein 4), a tumor suppressor, to prevent the binding of miR-21." (PMID 35884580, 2022). "In cancer cells, decreases in nuclear PDCD4 have been correlated with tumor progression." (PMID 36552834, 2022). "Furthermore, it has been found that in many transformed cells, although downregulated, PDCD4 is cytoplasmic yet predominantly in the nucleus of equivalent quiescent controls, indicating that the protein acts as a tumour suppressor in the nucleus." (PMID 35847932, 2022). "PDCD4 participates in tumor evolution, cancer progression and metastatic processes." (PMID 35402235, 2022). "Upregulation of miR-208a-3p by targeting PDCD4 could inhibit apoptosis in GC cell lines and enhance tumor growth in xenograft mice." (PMID 35402235, 2022).
tumor (continued). "These cells subsequently formed tumours that were smaller than the controls (formed by the injection non-transfected cells), had diminished miRNA-196a2 expression, decreased proliferation and increased PDCD4 expression." (PMID 35847932, 2022). "Erioflorin may act as a β-TrCP inhibitor, stabilizing the tumor suppressor Pdcd4 by inhibiting the β-TrCP1/Pdcd4 interaction and thus exhibiting antitumor potential." (PMID 34943817, 2021). "Besides tumor cells, PDCD4 is also expressed by cytotoxic T-lymphocytes where its expression is regulated by CTLA-4 and important for T-cell differentiation." (PMID 33801444, 2021). "Additionally, the expression and role of PDCD4 on B cells and mast cells will need to be elucidated in the context of anti-tumor immunity." (PMID 33801444, 2021). "PDCD4 (programmed cell death protein 4) inhibits tumor promoter-induced neoplastic transformation." (PMID 34917513, 2021). "Then in 1999, PDCD4 was firstly described as a tumor suppressor by Cmarik's group, which found that PDCD4 could inhibit neoplastic transformation in mouse JB6 cells." (PMID 33744861, 2021). "Individuals with high total tissue PDCD4 expression had longer survival from the time of brain metastasis diagnosis (log-rank test, p = 0.026; RR 0.54; Lower CL 0.3; Upper CL 0.93), and the same was seen in cases with high nuclear PDCD4 tumor cell expression (log-rank test, p = 0.004)." (PMID 33801444, 2021). "MiR-21 has also been linked to human tumor invasion and metastasis by negatively regulating targets that are adversely associated with metastatic capacity, such as PTEN, PDCD4, von Hippel-Lindau (VHL), TIMP3, Tropomyosin 1 (TPM1), and Serpin Family B Member 1 (SEPINB1)." (PMID 34066762, 2021). "Programmed cell death 4 (Pdcd4) as a tumor suppressor has been discovered for several years." (PMID 34772918, 2021). "In addition, miR-21 negatively suppresses programmed cell death 4 (PDCD4) tumor and regulates the downstream signaling targets in the row of colorectal cells." (PMID 35083006, 2021). "Accordingly, PDCD4 overexpression inhibits cancer cell proliferation and tumor growth." (PMID 34606825, 2021). "PDCD4 is known for its extensive role as a tumor suppressor and apoptosis activator." (PMID 34359600, 2021). "In addition, ROS promote gastric cancer by upregulating the expression of miR-21, which subsequently downregulates the expression of programmed cell death 4 protein (PDCD4), a tumor suppressor gene that inhibits tumor progression and neoplastic transformation." (PMID 34679688, 2021). "PDCD4 is well known for its ability to inhibit tumor growth, metastasis, and invasion." (PMID 34771727, 2021). "miR-21 increases cell migration through TPM1 and PDCD4 in neoplastic disease." (PMID 33712063, 2021). "In addition to the tumor suppressor APC, PDCD4 plays an inhibitory role in tumor growth, metastasis, and invasion." (PMID 34771727, 2021). "After its induction, miR-21 targets mRNA encoding programmed cell death 4 (PDCD4), a proinflammatory tumor-suppressor protein that activates NF-κB by currently unknown mechanisms." (PMID 34940759, 2021). "Furthermore, MiR-21 contributes to cancer progression by targeting tumor suppressor mRNAs such as tropomyosin 1, programmed cell death 4 (PDCD4), phosphatase, and tensin homolog (PTEN)." (PMID 34287243, 2021). "In addition, our studies unraveled the upregulation of major pro-oncogenic drivers in ATC such as the E3-ubiqutin ligases DTL promoting the decay of tumor suppressors such as PDCD4 and the transferrin receptor TFRC (CD71)." (PMID 34885022, 2021). "In CRC, miR-21 promotes tumor invasion and metastasis via modulating the expression of multiple cancer-related genes, including Transforming Growth Factor Beta Receptor 2 (TGFβR2), PDCD4, and PTEN." (PMID 34066762, 2021). "Based on the researches before, PDCD4 is a tumor suppressor." (PMID 33744861, 2021).
tumor (continued). "Interestingly, loss or downregulation of PDCD4 expression has been observed in 68% of GIST and is associated with tumor progression." (PMID 34359600, 2021). "PDCD4 has complex roles dependent on not only its subcellular site of expression but also on whether it is expressed on tumor or immune cells in the microenvironment." (PMID 33801444, 2021). "Additionally, it is reported that PDCD4 can inhibit the invasion of tumor cells via maintaining E-cadherin level." (PMID 34905503, 2021). "PDCD4, a tumor deterrent, is frequently down-regulated in diverse types of cancer." (PMID 34905503, 2021). "The tumor suppressor gene, Pdcd4 is an endogenous inhibitor of BDNF translation." (PMID 33960267, 2021). "Of note, the expression of previously well-established in vitro targets of miR-21 having tumor-suppressive activity, i.e., Ppara, Pdcd4, Timp3, Spry2, Pten, and Hbp1, was unchanged with miR-21 deficiency in vivo in mice again highlighting a cell/organ context-dependent action of miR-21." (PMID 34638467, 2021). "PDCD4 expression in both tumor and nearby CD3+ T cells did not associate with either mutational status or administration of modern treatment regimens and remained an independent prognostic indicator." (PMID 33801444, 2021). "Since PDCD4 is known to regulate protein synthesis in tumor models and also act as a downstream component of the mTOR pathway, we postulated that it could have a role in molecular processes relevant to axonal function." (PMID 32747606, 2020). "Meanwhile, miR-21 could target chicken programmed death cell 4 (PDCD4) to suppress growth and apoptosis escape of tumor cells." (PMID 32806547, 2020). "Most of the studies addressing the function of human PDCD4 have employed various tumor cells, raising the question whether these studies fully reflect the function of human PDCD4 in normal cells." (PMID 32066800, 2020). "PDCD4 is a well-known tumor suppressor and is involved in apoptosis." (PMID 32040481, 2020). "Taken together, our data supports the role of PDCD4 in regulation of tumor angiogenesis." (PMID 33304903, 2020). "The autophagy system may contribute at least partly to suppress the levels of PDCD4 and result in the development and progression of tumor cells." (PMID 31952347, 2020). "The increased levels of PDCD4 by autophagy inhibition might be involved in suppressing tumor development and progression and contribute to the treatment of various cancers." (PMID 31952347, 2020). "Programmed cell death 4 (PDCD4) protein is a tumor suppressor that inhibits translation through the mTOR-dependent initiation factor EIF4A, but its functional role and mRNA targets in neurons remain largely unknown." (PMID 32747606, 2020). "SRSF3 and PDCD4 knockdown could prevent tumor cell apoptosis with decreased Caspase-3 activation and decreased amount of fragmented chromosomal DNA." (PMID 33072610, 2020). "Down-regulation of PDCD4 expression in tumor cells occurs by different mechanisms." (PMID 32066800, 2020). "For instance, inhibition of miR-21 could suppress CSCC cell growth and invasion by targeting two tumor suppressors, PDCD4 and PTEN." (PMID 32161621, 2020). "Past researches have identified PDCD4 as a tumor suppressor in HCC." (PMID 33078826, 2020). "Notably, miR-93 inhibits PDCD4 by directly targeting its 3/-UTR resulting in enhanced migration of tumor cells via EMT stimulation." (PMID 32612456, 2020). "However, PDCD4 should be at least partly involved in the anti-tumor activities of anti-mir21 drug or other drugs to upregulate PDCD4 via inhibition of miR21 expression." (PMID 31075975, 2019).
tumor (continued). "Inhibiting the PDCD4 gene can lead to an increase in the metastasis potential of tumor cells." (PMID 30987065, 2019). "PDCD4 is a novel tumor suppressor that mutations have not been reported in cancer cells, but the protein levels are post transcriptionally controlled by environmental factors such as growth factors, interleukins, and TPA." (PMID 31075975, 2019). "The tumor-suppressor PDCD4 gene, which is commonly downregulated in CRC, is a target of miR-21." (PMID 30987065, 2019). "PDCD4 can combine with eukaryotic initiation factor-4A (eIF4A), thereby inhibiting its enzymatic activity, leaving the mRNA methylated decapping process unfinished and eIF4A-eIF4G complex unformed, thus inhibiting proliferation of tumor cells." (PMID 30760284, 2019). "This miR-21-medited downregulation of PDCD4 results in tumor progression." (PMID 31293964, 2019). "The arginine methylation may inhibit PDCD4-protein functions and allow the tumor to grow more aggressively." (PMID 31075975, 2019). "Besides the inhibition of protein synthesis, PDCD4 suppresses AP-1 transactivation that activates gene expression to stimulate cell proliferation, transformation, tumor invasion, and metastasis." (PMID 31075975, 2019). "Ectopic PDCD4 expression induces apoptosis of tumor cells so far as we have tested." (PMID 31075975, 2019). "The PDCD4-protein phosphorylated at S71 and S76 is then ubiquitinated by SCFβTRCP ubiquitin ligase and degraded in proteasomes resulting in the stimulation of cell proliferation and tumor progression." (PMID 31075975, 2019). "The combination therapy of these anti-tumor drugs and the compounds to upregulate PDCD4-protein levels, may be useful tools for cancer treatments." (PMID 31075975, 2019). "To answer this, we measured the 50% inhibitory concentration (IC50) (concentration of miRNA needed to achieve half-maximal silencing of the tumor suppressor PDCD4) of miR-499 by cotransfecting it at increasing concentrations, together with psi-WT or the miR-21 mutant plasmid (psi-M2)." (PMID 31235478, 2019). "Subsequently, we examined the potential target(s) for miR-21-5p using bioinformatics tools and we identified STAT3, a well-known oncogene, and PDCD4, an established tumor suppressor, as the top-ranking candidates from all three algorithms used (PITA, miRmap, and miRanda)." (PMID 31269723, 2019). "The targets of mir21 are not only PDCD4 but also other tumor suppressors such as PTEN mRNAs." (PMID 31075975, 2019). "Moreover, since the levels of PDCD4 expression in tumor cells are closely related to the sensitivity of antitumor drugs." (PMID 30760284, 2019). "PDCD4 has been identified as a tumor suppressor in multiple cancers." (PMID 30519392, 2018). "For instance, elevated PDCD4 expression inhibited tumor growth and promoted apoptosis in GC." (PMID 29930217, 2018). "Furthermore, by down-regulating the bioactivity of TGF-β1, DCN decreases the abundance of oncogenic microRNA (miR-21), a transcriptional inhibitor of a tumour suppressor named programmed cell death protein 4 (PDCD4), in a TLR2/4 independent manner." (PMID 29435195, 2018). "AKT phosphorylates PDCD4 and thus inhibits its tumour suppressor function." (PMID 29899543, 2018). "miR-21 binds to the 3′-UTR of tumor suppressor PDCD4 and suppresses its translation." (PMID 28881718, 2017). "The tumor-suppressor role of PDCD4 has been characterized well, and PDCD4 knockdown could significantly promote cell growth." (PMID 28854977, 2017). "PDCD4 plays a pivotal tumor-suppression role in the occurrence and development of various cancers." (PMID 28981115, 2017). "Moreover, miR-21 shut down in BEAS-2B cells also inhibited the chronic Cr(VI)-induced suppression of its target tumor suppressor, PDCD4." (PMID 28881718, 2017). "The tumor suppressor PDCD4 was down-regulated in all cancer patients enrolled in the study." (PMID 29091952, 2017). "The down-regulation of PDCD4 has been correlated with tumor stage and nodal metastasis." (PMID 27885434, 2017).
tumor (continued). "PDCD4, an important tumor suppressor in CRC, has been reported to be regulated by TIA1." (PMID 28257633, 2017). "PDCD4 is involved in cell apoptosis, neoplastic transformation, and tumor progression." (PMID 29091952, 2017). "Assuming that miR-17-5p inhibition would restore protein expression of tumor suppressive miR-17-5p targets Programmed cell death 4 (PDCD4) and Phosphatase and tensin homolog (PTEN), human TNBC cells were transfected with antisense oligonucleotides against miR-17-5p." (PMID 29050357, 2017). "Regulation of PDCD4 by miR-23a/b may explain why the upregulation of miR-23a/b during gastric carcinogenesis promotes tumor growth." (PMID 28981115, 2017). "In transgenic mice, PDCD4 suppressed tumor promotion and progression to carcinoma." (PMID 29091952, 2017). "miR-21 binds to the 3′-UTR of the tumor suppressor PDCD4 to suppress its translation." (PMID 27323401, 2016). "Inhibition of miR-21 or overexpression of PDCD4 results in decreased tumor formation and growth." (PMID 27323401, 2016). "Restoring PDCD4 production in tumor cells can be used as a method to control oncologic disease." (PMID 27634902, 2016). "Thus, upregulation of oncogenic miR-223, -31, and -21 is accompanied by down-regulation of their respective tumor suppressor target Fbxw7, Stk40 and Pdcd4." (PMID 26918602, 2016). "Furthermore, 30 of the 36 tonsil cancers examined by semi quantitative immunohistochemistry showed reduced expression of PDCD4 in tumour cells relative to the surrounding normal epithelial cells." (PMID 26867589, 2016). "PDCD4 could influence different cellular translation levels as well astranscription pathways in different tumor entities." (PMID 27240294, 2016). "PDCD4 is a tumor suppressor and an inhibitor of protein translation." (PMID 26867589, 2016). "Our results indicated a strong negative association of PDCD4 expression with tumor size and differentiation status of solid tumors." (PMID 27852288, 2016). "PDCD4 is a tumor repressor, suppressing tumor growth through different mechanisms." (PMID 26659076, 2016). "PDCD4 is known as a pro-apoptotic and tumor-suppressing gene." (PMID 27542230, 2016). "Additionally, Fbxw7, Pdcd4, and Stk40 (tumor-suppressor targets of miR-223, -21, and -31) were downregulated in marked-ZD cohort." (PMID 26918602, 2016). "Additionally, PDCD4 overexpression attenuated the growth-promoting effects of miR-181b, suggesting that miR-181b promotes tumor growth by silencing PDCD4." (PMID 27647131, 2016). "To explore whether PDCD4 consistently acts as a tumor suppressor and positive prognostic marker for solid tumors, we conducted an updated meta-analysis to evaluate the clinical significance and prognostic value of PDCD4 in human cancers." (PMID 27852288, 2016). "For the tumor suppressor PDCD4, strong staining was observed in both NM-2C5 and CL16." (PMID 26317550, 2015). "Moreover, a conserved protein locus has been identified in the PDCD4 sequence, through which miR-21 regulates PDCD4 expression to induce tumor invasion and metastasis." (PMID 26252635, 2015). "Indeed, we observed an increased ProMISe and a coherent decreased PDCD4 expression in tumor (right)." (PMID 24609385, 2014). "PDCD4 was originally identified as a tumor-related gene in humans." (PMID 25364579, 2014). "TWIST1 and PDCD4 expression was associated with the degree of tumor differentiation but not sex or age (p = 0.021 and p = 0.013)." (PMID 25144746, 2014). "Downregulation of PDCD4 is related to the tumor differentiation in digestive tract cancers." (PMID 25144746, 2014). "The tumor suppressor PDCD4 can bind to eIF4A or eIF4G and inhibit translation." (PMID 25144746, 2014).